MMP7 (matrix metallopeptidase 7)
Diseases named in the same sentence as MMP7 in open-access papers (continued):
Sharing a sentence is not in itself a finding about the gene and the disease.
COVID-19 (continued). "In addition, studies in adult COVID-19 have reported that circulating levels of MMP-7 are potential biomarkers of disease severity in patients requiring invasive mechanical ventilation." (PMID 36544496, 2022). "Since we had evidence of increased expression of MMP-14 and MMP-7 in COVID-19 lung tissue by proteomics reanalysis, both described activation pathways that could be effective in TAF samples to produce active-MMP-2 and active-MMP-8." (PMID 35625532, 2022). "MMP-7 could also be a marker for the persistence of lung lesions post-COVID-19." (PMID 35327637, 2022). "MMP-7 is a protease that, among other functions, breaks down the extracellular matrix deposited in the lung after injury, and one study has suggested that it could be a novel biomarker for COVID-19 ARDS recovery." (PMID 35327637, 2022). "Both MMP7 and MMP9 are being studied as potential biomarkers of disease severity and predictors of clinical outcomes in COVID-19." (PMID 38803919, 2024). "Further research is needed to elucidate the potential interplay between MMP7/MMP9 and FasL and their contributions to COVID-19 pathogenesis." (PMID 38803919, 2024). "The objective of this study is to evaluate interactions of MMP7/MMP9 with FasL and suggest therapeutic targets against COVID-19." (PMID 38803919, 2024). "The best solution of the docked MMP7-FasL and MMP9-FasL was selected to build blood-like conditions resembling healthy patients and special fever and hyponatremia COVID-19-like conditions." (PMID 38803919, 2024). "MMP7-FasL (Healthy), MMP7-FasL (COVID-19), MMP9-FasL (Healthy), and MMP9-FasL (COVID-19) systems showed 0, 1, 4, and 2 salt bridges, indicating MMP9 had more salt bridges." (PMID 38803919, 2024). "We analyzed bonds, short-range energies, and free binding energies to draw conclusions on the interaction of MMP7/MMP9 and FasL to gain insights into COVID-19 immunopathology." (PMID 38803919, 2024). "Overall, in both COVID-19 and normal conditions, the number of interacting residues and surface area was higher for MMP9 compared to MMP7 group." (PMID 38803919, 2024). "Our study showed a consistent upregulation of MMPs (MMP1, MMP7, MMP10, and MMP12) in post-COVID-19 individuals, suggesting ongoing remodeling processes in individuals that experienced mild disease." (PMID 36405747, 2022). "MMP-7, TGF-β, IL-10, IL-7, TNF-α, and IL-6 were correlated with high lung involvement in COVID-19 patients." (PMID 36286038, 2022). "Metalloproteases have a longstanding link to the progression of respiratory damage, and MMP-2, MMP-3, MMP-7, and MMP-9 have all been shown to correlate with COVID-19 severity." (PMID 36298651, 2022). "The results show that MMP-7, TGF-β, IL-10, IL-7, TNF-α, and IL-6 were significantly correlated with high lung involvement in COVID-19 patients." (PMID 36286038, 2022). "Research on the interaction between MMP7/MMP9 and FasL in COVID-19 is still relatively limited." (PMID 38803919, 2024). "Moreover, in both COVID-19 and normal conditions, the number of interacting residues and surface area was higher for MMP9 compared to MMP7 group." (PMID 38803919, 2024). "Our study provided insights into the interaction between MMP7/MMP9 and FasL in COVID-19." (PMID 38803919, 2024). "While there is currently limited information on the specific interaction between MMP7/MMP9 and FasL in COVID-19, it is possible that they may act synergistically or independently in the immune response and tissue damage observed in severe cases of the disease." (PMID 38803919, 2024). "Elevated levels of MMP7 and MMP9 have been observed in severe cases of COVID-19." (PMID 38803919, 2024). "MMP-7, TGF-β, CCL2, CCL-3, CXCL-10, G-CSF, IFN gamma, IL-10, IL-2, IL-4, IL-6, IL-7, TNF-α, IL-6, and IGF-1 were studied for their correlation with mortality in all 40 COVID-19 patients." (PMID 36286038, 2022).
COVID-19 (continued). "The remaining post-COVID-19 signature shows good agreement with single-cell RNA sequencing data and contains, among others, proteins related to TGFβ signaling, maintenance of the ECM (TGFβ1, BMP-6, MMP1, MMP7), and TNF-signaling (TNFα, TWEAK)." (PMID 36405747, 2022). "MMP-7, TGF-β, CCL2, CCL-3, CXCL-10, G-CSF, IFN gamma, IL-10, IL-2, IL-4, IL-6, IL-7, TNF-α, IL-6, and IGF-1 were studied for their correlation to lung involvement in COVID-19 patients." (PMID 36286038, 2022). "The role of MMP-7 in COVID-19 has not been reported; however, previous studies of non–COVID-19 acute lung injury have shown higher circulating levels of MMPs that associate with worse disease severity and clinical outcomes." (PMID 34111030, 2021). "Higher values of MMP-7 were also observed in another study in patients who had fibrotic lesions detected in the CT scan compared to patients who did not develop such lesions after being diagnosed with COVID-19 during the early stages of the pandemic." (PMID 36551272, 2022). "This target proteomics approach indicated that MMP-2, MMP-7, MMP-8, and MMP-14 figured out the COVID-19 perturbation with a significant increase compared to non-COVID-19 individuals." (PMID 35625532, 2022). "It appears partly reasonable with our results from proteomics reanalysis, which showed a significant increase in detection of MMP-2, MMP-7, MMP-8, and MMP-14, but not the expression of the MMP-9 protein, in lung tissue from COVID-19 compared to non-COVID-19 subjects." (PMID 35625532, 2022).
glioma (20 papers, 2012 to 2024). A benign or malignant brain and spinal cord tumor that arises from glial cells (astrocytes, oligodendrocytes, ependymal cells). "This study demonstrated that high-risk genes (LAMB4, MMP1, MMP7) promote glioma progression and negatively correlate with patient prognosis." (PMID 37335645, 2023). "We subsequently found that ADAMTS20 and FREM3 were interrelated lower risk of glioma using Cox regression analysis, whereas LAMB4, MMP1, and MMP7 showed high risk of glioma." (PMID 37335645, 2023). "After 24 h of treatment with OAnano, U87 glioma cells expressed about 40% less MMP-7 mRNA compared with the control group." (PMID 32194806, 2020). "It promotes the invasion of gliomas through upregulation of the expression of matrix metalloproteinase-7 (MMP-7), matrix metalloproteinase-9 (MMP-9), and vascular endothelial growth factor (VEGF)." (PMID 32650527, 2020). "Out of the well-predicted genes, CDK4, MMP7, MYCBP, and TMEM59 in gliomas and LCP1 in RCC have been implicated in multiple cancer types." (PMID 32194984, 2020). "As a result, OAnano impeded the migration and invasion of U87 glioma cells through inhibiting MMP-7 and disrupting formation and distribution of cytoskeletal protein." (PMID 32194806, 2020). "After overexpression of MMP7, the proliferation and invasion of glioma were enhanced." (PMID 37335645, 2023). "Moreover, a notable reduction of Vimentin and MMP-7 was noted, which contributed to the round shape and less protrusions in U87 glioma cells after treatment, which eventually led to the disability of migration and invasion." (PMID 32194806, 2020). "Additionally, the mRNA levels and protein expression levels of c-Myc, MMP-7 and cyclinD1 were significantly decreased in stable expression glioma cells with CCAT2 shRNA." (PMID 27833083, 2016). "MMP7 and MMP9 are related to ECM remodeling and transcripts of both MMPs are up-regulated in high grade gliomas." (PMID 38272115, 2024). "For the sake of clarifying the expression of BMGs in glioma, this study screened 9 BMGs that were upregulated in glioma (FBN2, FREM3, Lamb4, MEP1A, MMP1, MMP7, OPTC, EVA1A, and ADAMTS20) from TCGA -GTEX expression matrix." (PMID 37335645, 2023). "Current research has shown that glioma cells frequently activate the perk arm of the UPR by increasing the levels of the metalloproteinases (MMPs) MMP2 and MMP7, which promote the epithelial-mesenchymal transition (EMT)." (PMID 36727065, 2022). "In addition, C–X–C motif chemokine receptor 4 (CXCR4), C–X–C motif ligand 3 (CXCL3), and matrix metallopeptidase 7 (MMP7), also considered as positively correlated genes, were reported as oncogenic genes and facilitate growth, invasion, migration, and chemoresistance in gliomas." (PMID 34868960, 2021). "In the validation cohort of glioma patients, we found that CCN4, LGR6, MMP7 and TCF7 were obviously upregulated." (PMID 34852024, 2021). "The results revealed that knockdown of TROAP drastically downregulated the level of MMP2, MMP7, MMP9, RHOA, RHOA, ROCK1 protein in U251 glioma cell lines compared to control group (p < 0.05)." (PMID 34077623, 2021). "FOXD2-AS1 promoted glioma proliferation, invasiveness and EMT by acting as a ceRNA to sponge miR-506-5p, thus regulating the protein levels of MMP7, MMP9, N-cad, E-cad and vimentin." (PMID 33336050, 2020). "In the current study, IHC analysis of Vimentin and RT-PCR detection of MMP-7 showed that the expression levels of Vimentin and MMP-7 in U87 glioma cells were decreased in OAnano group, suggesting that OA impeded the migration and invasion of U87 glioma cells." (PMID 32194806, 2020). "Previously, leptin was reported to be able to increase the expression of MMP-2, MMP-7 or MMP-9 in different cancer cells, as well as the expression of MMP-13 in glioma cells." (PMID 25948792, 2015). "The expression of NFAT1 was significantly correlated with that of COX-2 (R = 0.209, P<0.05), MMP-7(R = 0.404, P<0.01) and MMP-9 (R = 0.414, P<0.01) in gliomas." (PMID 23762456, 2013).
glioma (continued). "Our data indicated that the Wnt pathway activation related genes such as CCN4, FOSL1, LGR6, MMP7, RAC2, SERPINF1 and TCF7 were upregulated, while Wnt pathway inactivation related gene such as CXXC4 was downregulated in radiotherapy treated glioma patients from TCGA database." (PMID 34852024, 2021). "In gliomas, HOTAIR was described to promote invasion through upregulation of MMP-7, MMP-9 and VEGF." (PMID 33375038, 2020). "Knockdown of FOXD2-AS1 in glioma cells significantly inhibited cell proliferation, migration, invasion and epithelial–mesenchymal transition (EMT) and regulated the expression of CDK2, cyclinE1, P21, MMP7 and MMP9." (PMID 33336050, 2020). "MMP7 codes for a metastatic promoting protein, HERC5 is an ubiquitin ligase that may be involved in malignancy, SLC7A11 is a part of the anionic amino acid transport system and was highly expressed in early stages of glioma, and LPHN2 has a role in cell adhesion." (PMID 26515461, 2016). "Moreover NFAT1, COX-2, MMP-7 and MMP-9 were simultaneously highly expressed in GBM, but not in low-grade gliomas." (PMID 23762456, 2013).
biliary atresia (19 papers, 2012 to 2026). A rare, biliary tract disease characterized by progressive obliterative cholangiopathy of the intra- and extrahepatic bile ducts, occurring in the embryonic/ perinatal period, leading to severe and persistent neonatal jaundice and acholic stool. "The study conclusively demonstrates the diagnostic value of serum MMP-7 as a biomarker for biliary atresia in the Chinese pediatric population, establishing age-specific cutoff values for improved accuracy." (PMID 38978022, 2024). "The results also showed that the serum level of MMP-7 above 1.43 ng / ml was a predictor of biliary atresia in neonates with cholestasis (diagnostic accuracy, 88%)." (PMID 35717157, 2022). "The aim of this study was to evaluate the serum level of matrix metalloproteinase 7 (MMP7) in infants with cholestasis and the diagnostic values of this biomarker to differentiate biliary atresia (BA) from other causes of cholestasis." (PMID 35717157, 2022). "In the liver, MMP7 is expressed by hepatocytes, biliary epithelial cells and Kupffer cells, and increased MMP7 expression has been associated with cirrhosis, biliary atresia-associated fibrosis and HCC migration and invasion." (PMID 27861569, 2016). "MMP7 demonstrated good accuracy to differentiate biliary atresia from other causes of cholestasis." (PMID 35717157, 2022). "Conventional liver function tests combined with serum MMP-7 represent a simple, reliable, noninvasive approach for early differentiation of biliary atresia." (PMID 42099523, 2026). "Ultrasound and serum matrix metalloproteinase-7 (MMP-7) hold great value in distinguishing biliary atresia (BA) from other cholestatic diseases." (PMID 41217622, 2025). "The term “diagnosis” illustrates the great significance of preoperative diagnosis, and early differentiation of CCs from other biliary disorders such as biliary atresia by prenatal ultrasound and MMP7 monitoring is the focus of clinical research." (PMID 40718413, 2025). "This was done to quantify serum MMP-7 expression in infants with biliary atresia and congenital heart disease." (PMID 39483898, 2024). "Matrix metalloproteinase 7 (MMP-7) is a novel biomarker for diagnosis of biliary atresia (BA), the most common cholestatic liver disease in infancy." (PMID 39483898, 2024). "Due to the higher specificity and sensitivity of MMP7 than GGT, this biomarker demonstrated good accuracy to differentiate biliary atresia from other causes of cholestasis." (PMID 35717157, 2022). "Previous studies have reported an increase intrahepatic matrix metalloproteinase-7 (MMP-7) expression level in infants with biliary atresia." (PMID 35717157, 2022). "To date, a few studies have established an association between serum MMP-7 and biliary injury in biliary atresia (BA) patients, and no specific report has studied the performance of serum MMP-7 in CDCs." (PMID 38914992, 2024). "Serum matrix metalloproteinase-7 (MMP-7) is significant in differentiating biliary atresia (BA)." (PMID 38034822, 2023). "In a study of pediatric cholestatic liver disease, endoglin, along with interleukin-8 (IL-8) and matrix metalloproteinase-7 (MMP-7), showed a significant correlation with increased liver stiffness in children with biliary atresia." (PMID 39199400, 2024). "The sensitivity and specificity of MMP7 to differentiate biliary atresia from nonbiliary atresia cholestasis in our study was 95.5% and 94.5%, respectively." (PMID 35717157, 2022).
fibrosis (19 papers, 2007 to 2026). the formation of excess fibrous connective tissue in an organ or tissue in a reparative or reactive process. "Fibrosis-associated biomarkers such as Matrix Metalloproteinase-7 (MMP-7), Monocyte chemoattractant protein-1 (MCP-1), and Dickkopf-3 (DKK3) have been proposed as indicators of progressive CKD, particularly in high-risk patients." (PMID 40428218, 2025). "Mice lacking MMP7 are relatively protected from bleomycin-induced fibrosis, and increased blood levels of MMP7 have been shown to distinguish IPF patients from controls and other diseases and are the most validated markers of increased mortality in IPF." (PMID 35698166, 2022). "Moreover, our investigation demonstrates that a mutation at position 123 of the SFTPC gene, situated within the BRICHOS domain in whales, induces an upregulation of the lung fibrosis marker proteins MMP7 and α-SMA." (PMID 38575860, 2024). "MMP-7 is an important matrix metalloproteinase involved in liver fibrosis and cancer metastasis." (PMID 31235809, 2019). "In line with this, we found an increased ACE, MMP2, and MMP7 mRNA expression, but also reduced APEH, ECE1, MBP, and NEP in samples with an advanced fibrosis grade." (PMID 39201455, 2024). "For instance, it has been documented that mice lacking MMP-7 are protected from bleomycin-induced fibrosis." (PMID 20949050, 2010).
diabetes (18 papers, 2013 to 2025). "In our analysis, among the proteins that showed an association with self-reported diabetes, a matrix metalloprotease enzyme, MMP7, was positively associated with diabetes in all three population groups." (PMID 35365620, 2022). "Notably, MMP-10 was significantly associated with MACE in PAD patients with diabetes, while MMP-7 showed an association in female PAD patients, underscoring their relevance in specific high-risk subgroups." (PMID 40563493, 2025). "In diabetic mice (DM), myocardial fibrosis is clearly related to the expression of MMP7, MMP11, MMP13, and MMP16 in myocardial tissue." (PMID 33014530, 2020). "The optimum multivariable prediction model from the 33 analytes remaining after controlling for missing data and 4 clinical co-variates (age, BMI, APRI and diabetes), incorporated MMP7, MMP1, AFP, PDGF-AA, APRI and age (AUROC = 0.928, “ELISA model”)." (PMID 27861569, 2016). "The best model for predicting liver inflammation (METAVIR grade 2–3) comprised CXCL10, TIMP1 and APRI (AUROC = 0.798); whereas the best model for predicting steatohepatitis incorporated IL8, ADIPOQ, MMP2, MMP7, age, BMI and diabetes (AUROC = 0.857)." (PMID 27861569, 2016). "Our group has discovered that diabetes causes an imbalance of increased proNGF at the expense of mature NGF due to impaired MMP-7 activity in clinical and experimental diabetes." (PMID 25853140, 2015). "Third, subgroup analyses revealed that MMP-10 was predictive of 2-year MACE in PAD patients with diabetes, while MMP-7 was predictive in female PAD patients, suggesting these proteins may serve as prognostic markers for specific high-risk subgroups." (PMID 40563493, 2025). "Notably, AGE accumulation in patients with diabetes mellitus suppressed the expression levels of MMP7 in the epidermal stem cells, suggesting that MMP7 may be important for wound healing processes." (PMID 38732212, 2024). "Logistic regression modelling revealed that serum MMP7 remained independently associated with clinically significant fibrosis (LSM ≥ 8.2 kPa) after accounting for potential confounding factors (patient age, gender, BMI and diabetes (adjusted Odds Ratio (aOR) 9.65, 95% CI 3.09–30.13)." (PMID 33536476, 2021). "After adjusting for baseline factors—including age, sex, dyslipidemia, hypertension, smoking status, diabetes, CHF, CAD, and prior stroke—plasma levels of MMP-10 and MMP-7 remained independently correlated with 2-year MACE in PAD patients." (PMID 40563493, 2025). "After comparing and contrasting the renal parameters of the male and female participants, we discovered that male diabetics had higher serum urea, creatinine, urine albumin, urine creatinine, urine ACR, and normalized urine MMP-7 levels than female diabetics." (PMID 39246865, 2024). "In univariate analysis, age, CAD, diabetes, CAVI, serum MMP-7, MMP-9, and TIMP-1 correlated with established carotid atherosclerosis." (PMID 37759829, 2023). "Another peculiar interaction pattern was detected with MMP7 as its expression was reduced by T2DM in the tumor, while diabetes alone slightly upregulated that gene in normal gut epithelial cells." (PMID 32971867, 2020). "When adjusted with demographics (age, sex), history of diabetic mellitus, RRF, peritoneal dialysis adequacy (peritoneal KT/V) and dialysate glucose concentration, the dialysate MMP‐7 still significantly correlated to peritoneal UF volume (β = −76.1, P = 0.039)." (PMID 34117704, 2021). "Serum MMP7 was associated with clinically significant fibrosis (LSM ≥ 8.2), independent of age, gender, BMI and diabetes." (PMID 33536476, 2021). "The difference in median MMP‐7/Cr levels between people with DKD versus longstanding diabetes without DKD remained significant after additional adjustment for hemoglobin A1c (P < 0.001)." (PMID 24793984, 2014).
diabetes (continued). "In conclusion, using carefully characterized assays, we find that in people with type 1 diabetes who have DKD, urine concentration of AGT, MMP‐7, and gremlin‐1 are markedly higher than in individuals with new onset of diabetes or those with longstanding diabetes without DKD." (PMID 24793984, 2014). "Creatinine‐adjusted urine MMP7 concentration was sixfold higher in people with type 1 diabetes and DKD than those with no DKD and 6.7‐fold higher than in newly diagnosed diabetes." (PMID 24793984, 2014). "Among the MMPs examined, MMP-1, MMP-2, MMP-3, and MMP-7 were detected in all vitreous samples from patients with PDR and control patients without diabetes." (PMID 24392031, 2013).